HK2 (hexokinase 2)
Diseases named in the same sentence as HK2 in open-access papers (continued):
Sharing a sentence is not in itself a finding about the gene and the disease.
tumor (continued). "In instances where tumor cells experience a severe glucose deficit, HK1 assumes a more prominent role in facilitating glycolytic reactions compared to HK2, owing to its lower Km." (PMID 37741973, 2023). "We used a sequential, multiplex staining protocol in which six markers were analyzed simultaneously: CD15 (neutrophil marker), pan-cytokeratin (CK; tumor marker), HIF-1α, GLUT1 and HK2 (glycolytic markers), and DAPI (nuclear marker)." (PMID 36614196, 2023). "IHC staining observed lower HK2 and PKM2 expression in tumors after circCOL5A1 knockdown, and Western blot assessed lower protein expression of tumor PRKCSH and Ki-67." (PMID 37660068, 2023). "Here, only HIF-1α + GLUT1+ neutrophils were proportionally increased in PDAC tumor tissue (23.21%) compared to adjacent matched normal tissue (8.17%), while the proportion of HIF-1α + HK2+ and GLUT1 + HK2+ neutrophils was similar between the two groups." (PMID 36614196, 2023). "The expression and activity of key glycolytic enzymes, such as hexokinase-2 (HK2), glucose transporter type 1 (GLUT1) and pyruvatekinase M (PKM), can affect the glycolysis of tumor cells and thereby affect tumor proliferation." (PMID 37060505, 2023). "As reported, HK2 is dramatically up-regulated in HCC tissues, while HK2 knockdown dampens HCC cell aerobic glycolysis and tumor growth." (PMID 37129745, 2023). "In multivariate analysis, tumour size, ASPP2 and HK2 expression status were shown as significant independent predictors of RFS and OS." (PMID 36752127, 2023). "We also performed IHC analysis of SW480 xenograft tumor tissues and confirmed that the protein levels of the glycolytic enzymes GLUT1, GLUT4, HK2, LDHA and LDHB were lower in xenografts from PROX1 knockdown cells than in those from control cells." (PMID 36594098, 2023). "The mRNA expression of these genes in TCGA-PRAD samples was determined, and in both non-paired and paired samples, HK2, HK3 and ADPGK were overexpressed, while GCK and HK1 were downregulated in tumor samples compared with normal tissues." (PMID 38082365, 2023). "Hexokinase 2 (HK2), a rate-limiting enzyme, exhibits elevated expression levels in neoplastic tissues and is closely related to tumor energy metabolism." (PMID 37834257, 2023). "Many other tumor promoters (such as the epidermal growth factor receptor pathway substrate 8 (Eps8), hexokinase 2 (HK2), galactose lectin-3, etc.)are degraded via the CMA pathway to deactivate them and inhibit tumor growth." (PMID 37509689, 2023). "Importantly, although less significant than its effect on G6PD, p52-ZER6 might also affect the expression of other glucose metabolism-related genes, such as FH, PKM2, TIGAR, LDHA, GLUT1, and HK2, thereby contributing to tumor metabolic reprogramming through multiple pathways." (PMID 36977688, 2023). "A significant correlation between HK2, ASPP2 expression and tumour volume was observed (p = 0.027): patients with ASPP2‐low and HK2‐high expression were prone to having a larger tumour volume." (PMID 36752127, 2023). "Emerging studies have shown the upregulation of enzymes hexokinase-2 (HK2), phosphofructokinase, enolase 1 (ENO1), and pyruvate kinase M2 (PKM2) in animal models and human cells stimulated with tumor extract solution." (PMID 37426676, 2023). "Several studies have indicated that increased FDG uptake has relationships with expression levels of hexokinase 2 (HK2), glucose transporters (GLUTs) and monocarboxylate transporters (MCTs) in DLBCL tumor cells." (PMID 37367892, 2023). "These inhibitors act on HK2, PFKFB3, GAPDH, PKM2, and LDH, respectively, effectively inhibiting glycolysis and tumor proliferation." (PMID 37582735, 2023). "Many miRNAs target HK1 or HK2 to affect glucose metabolism in CRC and interfere with tumor proliferation." (PMID 37576895, 2023). "In univariate analysis, tumour size, ASPP2 and HK2 expression status were found to be the prognostic factors for RFS and OS (p < 0.05)." (PMID 36752127, 2023).
tumor (continued). "The USP7/c‐Abl axis promotes NSCLC cell glycolysis process by stabilizing hexokinase‐2 (HK2) protein, therefore promoting NSCLC tumour progression." (PMID 38082439, 2023). "We observed that the expression levels of GLUT1 (SLC2A1) and the glycolytic rate-limiting enzymes HK2 and PFKP were increased in response to stress both in mRNA and protein levels in CRC cells and tumor tissues." (PMID 37151872, 2023). "The xenograft tumor model indicated that FDX1 OE significantly inhibited the growth of UCEC and attenuated the PCNA, HK2, PKM2, and Ki-67 expression." (PMID 37945610, 2023). "Apigenin has been demonstrated to decrease GLUT1, HK2, PKM2, and LDHA production in tumor cells, and galangin has been shown to bind to the PKM2 site." (PMID 37892405, 2023). "KIAA1429 knockdown substantially inhibited the tumor growth of CRC cells in vivo via reducing the m6A level and expression of HK2 mRNA." (PMID 37152066, 2023). "Consistent with the tumor volume data, SIRT6, HIF-1α, HK2 and Ki-67 protein levels were lower in the PC9/ER/shSIRT6 tumor tissue samples than in the PC9/ER/shCtrl tissue samples." (PMID 35915188, 2022). "In this study, both in vitro and in vivo experiments revealed that the proliferative activity and tumor growth was enhanced in HK2 over-expressed OVCA433 and SKOV3 cells, but attenuated in HK2 knocked-down A2870 cells." (PMID 35711830, 2022). "HK2, GAPDH, and PKM2 are the glycolytic enzymes, and elevated glycolysis is related to tumor progression and treatment resistance." (PMID 35742944, 2022). "The circ-ZNF609/miR-501-3p axis was targeted to upregulate the expression of hexokinase 2 (HK2), a key enzyme of glycolysis, and then improved the radioresistance of tumor cells both in vitro and in vivo." (PMID 35938040, 2022). "Hypoxia stabilizes HIF-1a which in turn increases expression of hexokinase-2 (HK2) in GBM cells that then promotes glycolysis and activation of factors that stimulate the transport of lactate to the extracellular space, and tumor growth and invasion." (PMID 36643416, 2022). "Western blot showed that a decrease in the expression levels of PKM2, GLUT-1, HK1, HK2, PKM1, and LDHA decreased in tumor cells and an inhibition of glycolysis and cell proliferation." (PMID 36284386, 2022). "HIF-1 activation increases many glycolytic enzymes, including hexokinase 2 (HK-2) and phosphofructokinase 1 (PFK1), which appear to be oncogenes required to mediate tumor initiation and growth." (PMID 36551540, 2022). "Next, the tumor tissues were sectioned and stained, and similarly, the results confirmed high expression of HIF-1α and glycolysis-related genes like LDHA, HK2, PKM2 in the control group and low expression in the shFAM83A-AS1 LUAD." (PMID 35002507, 2022). "Most commonly, lncRNAs sponge to corresponding miRNA and mRNA that target critical metabolic enzymes, such as PKM2, LDAH, HK2, and glucose transporter GLUT1, to modulate the expression of numerous oncogenes and tumor-suppression genes." (PMID 36072431, 2022). "Glycolytic enzymes, such as hexokinase 2 (HK2) and PKM2 isoenzyme, are highly expressed in TNBC cells and mediate glycolysis and tumor development, which activate NF-kB and its downstream target genes." (PMID 36109724, 2022). "This stabilization boosts glucose metabolism, notably by increasing hexokinase-2 (HK2) expression, and favors cell growth and tumor progression." (PMID 35326472, 2022). "Increased XBP1-s promotes glycolysis by positively regulating the expression of hexokinase 2 (HK2) and enhances tumor cell viability under hypoxia." (PMID 35269888, 2022). "Hexokinase (HK) plays a vital role in tumor glycolytic metabolism and includes HK1 and HK2 isoforms." (PMID 36532721, 2022). "In the tumor microenvironment (TME) increased activity of glucose transporter GLUT1 and hexokinase II (HK2) compensate for the irregular vascularization." (PMID 36048281, 2022).
tumor (continued). "Quantification of the IHC score was done to confirm the positive correlation observed between lncMMPA and tumor glycolytic enzyme expression, including GLUT1 and HK2 or TAM infiltration." (PMID 35986343, 2022). "Salidroside at 50 mg/kg/d significantly inhibits tumor growth, reduced the ENO1, HK2, and GLUT1 protein expression levels in MKN-45 and SGC-7901 cell xenografted mice in vivo." (PMID 36438836, 2022). "The results revealed that IMP4 silencing reduced the levels of GLUT1, HK2, PFKP, PKM2, and LDHA in LUAD cells and tumour tissues." (PMID 36317123, 2022). "Quantitative PCR, immunoblotting, and a colorimetric assay further confirmed the decreased expression and reduced enzyme activity of HK2, PFKP, and PKM2 in PyMT;Zeb1cKO tumor cells compared to PyMT cells." (PMID 35246504, 2022). "Silencing of RPN2 also inhibited the expression of HK-2, PDK1, and LDHA in these cells and decreased LDHA level in mouse tumor tissues." (PMID 35156537, 2022). "We observed that HK2 was elevated in 6/10 (60.0%) NSCLC tissues and its relative expression (expressed as ΔCt) was significantly higher (p = 0.019) in the tumor tissues (median = 6.57) compared to their corresponding non-cancerous tissues (median = 8.24)." (PMID 35805008, 2022). "Protein expressions of HK2, PFKM and PKM were found to be high in tumor tissues with cytoplasmic localization." (PMID 35328104, 2022). "CRC tumour samples had significantly lower MARCH8 levels (P < 0.0001) and significantly higher HK2 levels (P < 0.05) than those in normal colon tissues." (PMID 36064706, 2022). "Decreased expression of HK1 accelerates tumor malignancy through regulating energy metabolism, and there is an inverse relationship in the expression of HK1 and HK2 in cancer." (PMID 35626002, 2022). "In clinical specimens, we also found high expression of lncRNA CASC7 in tumours, and the expression levels of lncRNA CASC7 and HK2 were positively correlated." (PMID 35474307, 2022). "The up-regulation of the most important rate-determining enzymes in glycolysis, such as hexokinase 2 (HK2) and type M2 pyruvate kinase (PKM2, also known as tumor M2-PK), is promoted." (PMID 35563441, 2022). "A dual novel EGFR/HER2 inhibitor, KU004, can inhibit the expression of hexokinase II (HK2) through PI3K/AKT signaling pathway, thereby inhibiting glycolysis and tumor growth." (PMID 36059961, 2022). "In HCT116 Cells, wogonin inhibited the expression of HIF-1α and glycolysis-related proteins (HK2, PDHK1, LDHA) by inhibiting the PI3K/Akt signaling pathway, reduced glucose uptake and lactate production to combat drug resistance of tumor cell." (PMID 36339566, 2022). "High glucose levels can increase PD-L1 expression in tumor cells for tumor immune evasion by HK2-mediated NFκB activation and pancreatic insulin secretion, which in turn can activate PI3K-AKT in tumor cells to increase the Warburg effect." (PMID 39872073, 2022). "Activation of HIF-1 triggers a panel of down-stream genes (GLUT1, PGK1, HK2, PGM, LDHA and MCT4), and mediates tumor proliferation, angiogenesis, metastasis, cell invasion, migration and glucose metabolism, showing consistency with our results." (PMID 35927239, 2022). "We detected the expressions of glycolytic enzymes and membrane transporters, including GLUT1, HK2, PKM2, LDHA, and MCT4, in subcutaneous transplantation tumor models from WT and 5-FU-R HCT8 cells by IHC." (PMID 34998404, 2022). "Glucose metabolism activity in tumor cells is closely related to the expression of GLUT1, HK2, and LDHA, which are enzymes involved in glucose metabolism." (PMID 36267974, 2022). "In the present study, histidine supplementation in HCC cells reduced the expression of tumor markers related to glycolysis (GLUT1 and HK2), inflammation (pSTAT3), angiogenesis (VEGFB and VEGFC), stem cells (CD133), metastasis (Snail/slug), and cell migration." (PMID 35267513, 2022).
tumor (continued). "The removed tumor tissues were subjected to Western blot, and it was confirmed that the protein expression of HIF-1α and its downstream glycolytic genes GLUT1, HK2 and PDK1 in the HNK treatment group was significantly lower than that in the control group." (PMID 35350760, 2022). "C-myc can bind to the regulatory region of hexokinase 2 (HK2) and thus play an essential role in tumor aerobic glycolysis." (PMID 35431949, 2022). "The relative mRNA level of glycolytic genes showed that combination treatment considerably suppressed HK2 and GPI expression in the xenograft tumor tissues, indicating an in vivo inhibitory effect of ponatinib and sirolimus on tumor metabolism." (PMID 35681744, 2022). "Similarly, HK2 could also translocate to mitochondria and protect tumor cells from apoptosis." (PMID 36319992, 2022). "What’s more, hypoxia-inducible factor-1α (HIF-1α) is a key transcriptional regulatory protein that regulates an arrangement of hypoxia-sensitive proteins expression, such as PKM2, HK2, PFKP, to preserve the survival of tissue in tumor microenvironment." (PMID 36536346, 2022). "Remarkably, we found that exogenous histidine treatment induced a reduction in the expression of tumor markers related to glycolysis (GLUT1 and HK2), inflammation (STAT3), angiogenesis (VEGFB and VEGFC), and stem cells (CD133)." (PMID 35267513, 2022). "Key enzymes in glycolysis, such as hexokinase 2 (HK2), pyruvate kinase M2 (PKM2) and phosphofructokinase (PFK) have become new tumor biomarkers, so targeting these genes can turn off the nutrient and energy sources of tumors." (PMID 36015212, 2022). "In the same study, FSTL3 overexpression increased the expression of proteins involved in aerobic glycolysis, such as GLUT1, LDHA, HK2, and PKM2, resulting in a decrease in the pH of the tumor microenvironment and contributing to tumor cell immune evasion." (PMID 36325361, 2022). "Alkaloids: In HCT116 and SW620 cells, matrine inhibited the expression levels of downstream targets of glucose metabolism GLUT1, HK2 and LDHA by down-regulating HIF-1α mRNA and protein expression, consequently impacting tumor cell survival." (PMID 36339566, 2022). "Dysregulation of key metabolic genes, namely, HK2, PFKM, and PKM2, has the potential to disrupt glycolytic metabolism and remove additional barriers against tumor progression." (PMID 35328104, 2022). "Hexokinase 2 (HK2) depletion suppresses glycolysis and enhances OXPHOS, which further sensitizes tumor cells to metformin." (PMID 36147929, 2022). "Taken together, above results suggested that FGFR inhibition downregulated HK2 gene transcription via AKT-mTOR signaling, leading to the decrease of glucose uptake in the FGFRi-sensitive tumor cells." (PMID 36168616, 2022). "2-Deoxy-D-glucose (2-DG), a well-known inhibitor of glycolysis, sensitizes tumor cells to ADR and PTX in human osteosarcoma and NSCLC by suppressing HK2 expression." (PMID 36359776, 2022). "Highly glycolytic tumors with expression of HK2 and LDHA thus competitively deprive glucose from the TME to impair antitumor immunity and support tumor progression and metastasis in preclinical models of cancers such as sarcoma." (PMID 36358940, 2022). "In HCT116 and SW620 cells, wearnine decreased HIF-1 levels by activating p-VHL and triggered down-regulation of PFK-L, HK2 and PKM2, consequently limiting the glycolytic process of tumor cells and exerting anti-colorectal actions." (PMID 36339566, 2022). "Even though there are more hurdles to overcome for developing clinically applicable HK2 inhibitors, there could be promising combination agents to enhance immunotherapy or chemotherapy responses by releasing immune cells from metabolic competition and directly decreasing tumor cell survival." (PMID 36320008, 2022).
tumor (continued). "Overexpression of USP13 remarkably decreased the protein levels of glucose transporter-1 (GLUT1) and hexokinase-2 (HK2) and therefore reduced glucose uptake and lactate production, which are essential energy providers for tumor cells." (PMID 36188217, 2022). "PPI showed that HK2 was closely related to HK1, GPI, and HK3, all of which played an important role in tumor proliferation." (PMID 34708035, 2021). "Overexpression in tumor cells of the glycolysis enzyme HK2 suppresses glucose uptake and interferon gamma (IFN-γ) production in tumor-infiltrating lymphocytes (TILs)." (PMID 33922558, 2021). "Mechanistically, lncRNA-SLCC1 interacted with AHR and transcriptionally activated HK2 expression, the crucial enzyme in glucose metabolism, thereby driving the glycolysis pathway and accelerating CRC tumor growth." (PMID 33602893, 2021). "Interestingly, treatment with 3-BP and doxorubicin showed no synergistic inhibitory effect on LLC cell growth in vitro, while exposure of NPC with conditioned medium from 3-BP or/and doxorubicin pre-treated tumor cells could still up-regulate HK2 and ROCK2 expression as compared with untreated NPC." (PMID 34650057, 2021). "Overexpression of hexokinase 2 (HK2) and GLUT1 was attributed to the METTL3-m6A-IGF2BP2/3-dependent mechanism and further accelerated glycolysis to accelerate tumor growth." (PMID 33879256, 2021). "Immunohistochemistry results demonstrated that, in the tumor tissue of the TRAF6 shRNA group, Akt phosphorylation was substantially decreased, and the expression of hexokinase-2 was also dramatically reduced, which was in accordance with the in vitro results." (PMID 34409101, 2021). "Crucial enzymes in the glycolysis pathway, such as Hexokinase 2 (HK2) 29, 30, M2-type acetone kinase (PKM2) 8, 31 and phospho-fructosidase (PFK) 32, 33, have become tumor markers." (PMID 33994862, 2021). "BIRC5 and HK2 showed higher expression in MYCN amplified cell lines and tumor tissues consistently, whereas GRID2 and RNASEL showed the opposite trends." (PMID 34746127, 2021). "In several tumor types AKT is constitutively active, leading to HK2 phosphorylation on Thr-473 and to its localization on the OMM, where it inhibits cell death blocking mPTP opening." (PMID 33946854, 2021). "c-Myc has been demonstrated to increase the expressions of many tumor metabolic enzymes including glycolytic regulators HK2, PKM2, and LDHA to enhance the glycolysis in tumor cells." (PMID 33572615, 2021). "The key glycolytic enzymes, including GLUT1, HK2, and PKM2 are highly expressed in GBM and play important roles in cell growth and tumor development." (PMID 33931589, 2021). "Administration of a HK2 inhibitor induces pericyte-MLC2 driven tumor vasculature remodeling leading to enhanced drug delivery and efficacy against tumor growth." (PMID 34650057, 2021). "By real-time qPCR analysis, we found that CD73 knockdown can lead to significant down-regulation of glycolytic genes (GLUT1, HK2, ENO1, and LDHA) in tumor tissues from the subcutaneous xenograft model." (PMID 34659527, 2021). "It is important to note that HIF1A and c-Myc are both known to regulate the expression of tumor-specific isoforms of glycolytic proteins such as GLUT1, HK2, PKM, and LDHA, thereby diminishing the Warburg effect in cancer cells." (PMID 34692483, 2021). "Under conditions of PLK3 overexpression, expression levels of HK2 decrease, while silencing PLK3 increases the expression of HK2 in tumor cells." (PMID 34217310, 2021). "It requires GLUT1 protein on the cell surface for the internalization and hexokinase-2 enzyme for retention in tumor cells; but the expression of GLUT 1 transporters and hexokinase 2 is inconsistent in MM cells." (PMID 34586539, 2021). "In particular, miR-148a acts as a key tumor suppressor that controls sphere formation and CDDP resistance by targeting HK2." (PMID 34858863, 2021).